NF1 (neurofibromin 1)
Diseases named in the same sentence as NF1 in open-access papers (continued):
Sharing a sentence is not in itself a finding about the gene and the disease.
melanoma (continued). "Notably, the efficacy of this combinatorial treatment in melanoma cells is not influenced by BRAF, NRAS or NF1 mutational status, opening the possibility of using these compounds to treat melanoma expressing high levels of SOX2 and GLI1 irrespectively to their mutational status." (PMID 33958721, 2021). "To determine whether CAPN1 directly affects NF1 stability, we treated A375 or 74T melanoma cells with increasing concentrations of Calpain inhibitor I. A significant increase in NF1 levels was observed following the inhibitory treatment, suggesting that CAPN1 is indeed involved in NF1 stability." (PMID 30131853, 2018). "Furthermore, the apparent absence of neurofibromin and NF1 mRNA was recorded in a primary melanoma." (PMID 28637487, 2017). "But, whilst mutant NF1 is known to cooperate with RASopathy genes (RASA2, PTPN11, SOS1, RAF1 and SPRED1) in melanoma and although NF1 is found to be frequently mutated (25–30%) in melanomas harbouring wild-type BRAF and NRAS, it is curious that melanoma is not a tumour type associated with NF1." (PMID 28637487, 2017). "Therefore, melanoma screening of NF1 patients may be recommendable even if the NF1 genetic background may not result in a strongly enhanced melanoma incidence." (PMID 16961930, 2006). "In the literature, the triple-wild-type melanoma (TWM) refers to those where BRAF, NRAS and NF1 are not mutant." (PMID 36980598, 2023). "In line with prognosis, genetic alterations occurring in mucosal melanoma are different than those of cutaneous wild-type melanoma (BRAF, NRAS and NF1 negative)." (PMID 34571863, 2021). "Cutaneous melanoma can be divided into chronically sun-induced melanoma (CSID), non-chronically sun-induced melanoma (non-CSID) and the four genomic subtypes, BRAF, RAS, NF1, and triple wild-type." (PMID 34359771, 2021). "However, equine melanomas from mucosal‐like or mucocutaneous sites showed a landscape of driver genes that was less populated than human mucosal melanoma, and there were fewer recurrently mutated genes in common with human mucosal melanoma, with no mutations found in SF3B1, ATRX or NF1." (PMID 32652526, 2020). "Common genomic subtypes of human cutaneous melanoma (BRAF, RAS (N/H/K), and NF1 in 90% of cases) that engage oncogenic signaling through the MAPK pathway are less common in human non-cutaneous melanoma and in canine malignant melanoma (24% of cases here)." (PMID 30188888, 2018). "While the option of targeted therapy is available for patients with BRAF V600‐mutant melanoma, patients with melanomas of the RAS, NF1, or triple‐wild‐type subtypes usually have no efficient therapeutic option besides immunotherapy." (PMID 28267273, 2017). "Indeed, NF1‐09 (nonclassic MPNST) and SP‐01 (melanoma) presented higher IC50 values for Mirdametinib and Alisertib (> 100 μm) compared with NF1‐08 (9.267 and 12.59, respectively) and S462 (0.98 and 3.872)." (PMID 37798904, 2024). "In addition, therapeutic options for some non-eligible melanoma patients (for example, RAS mutant or triple BRAF/NRAS/NF1 wild-type melanoma patients) are more limited." (PMID 35159327, 2022). "Alterations of upstream effectors of RAS, such as NF1 or SPRED1, in mucosal melanomas could play this role, but there is currently not enough extensive genomic data on mucosal melanoma to confirm this hypothesis." (PMID 31398831, 2019).
melanoma (continued). "In total, only 9.6% of all cases in the cohort were negative for either of the genetic changes in BRAF, NRAS, NF1 and KIT, indicating that the majority of melanomas could potentially have activated MAPK pathway through these genetic alterations." (PMID 25909218, 2015). "Additionally, the limited gene panel did not include emerging melanoma drivers, such as TERT or NF1, which could improve detection and stratification in future studies." (PMID 40652269, 2025). "Interestingly, BRAF, NF1 and RAS were not significantly differentially methylated in melanoma tissues in relation to UV exposure, highlighting that UV exposure produces DNA methylation changes in genes that can be different from critical ones mutationally altered by the same environmental exposure." (PMID 35840550, 2022).
glioma (369 papers, 2008 to 2026). A benign or malignant brain and spinal cord tumor that arises from glial cells (astrocytes, oligodendrocytes, ependymal cells). "Afterwards, we focus on diagnostics of NF1-associated glial tumor manifestations, challenges, datasets, and review the current state of NF1 in Imaging to propose future directions with AI." (PMID 41168866, 2025). "Ulixertinib, a first-in-class ERK inhibitor, is currently being investigated in an early Phase I study (NCT05804227) enrolling adolescents and adults with MAPK-activated gliomas, including NF1-associated low-grade gliomas." (PMID 41374990, 2025). "NF‐1 deficiency in IDH‐wildtype gliomas, often seen in the mesenchymal subtype, is known to attract more macrophages." (PMID 40781854, 2025). "Per consensus recommendations for NF1-associated glioma, tumors were classified as probable LGG by radiographic features; biopsies were not standardly performed." (PMID 40296988, 2025). "Neurofibromin 1 (NF1), a well-known tumor suppressor gene, is frequently mutated in gliomas, particularly in the mesenchymal subtype." (PMID 40630952, 2025). "NF1-associated gliomas demonstrated a more favorable response to chemotherapy, likely due to their distinct tumor biology, including slower progression and less aggressive clinical behavior compared to sporadic gliomas." (PMID 41440192, 2025). "Another study (NCT04201457) is exploring the use of hydroxychloroquine in combination with trametinib (for BRAF fusion or NF-1 associated glioma) or with trametinib and dabrafenib (for BRAFp.V600E) in recurrent pLGGs or pHGGs)." (PMID 40422539, 2025). "Among NF1-associated gliomas, pilocytic astrocytomas of the optic pathway are the most common and primarily affect young children, necessitating a thorough diagnostic workup." (PMID 41168866, 2025). "MEKi are effective in treating people with NF1-associated clinical manifestations, including pNF and low-grade gliomas, but have demonstrated limited activity in preclinical models of NF1-MPNST." (PMID 41023593, 2025). "There have been significant advances in the treatment of glioma and NF-1 associated PNs over the past decade, which have been largely driven by the study of small molecule inhibitors." (PMID 40422539, 2025). "Alongside nerve sheath tumors, NF1 individuals are also at risk for developing various low- and high-grade gliomas." (PMID 41294711, 2025). "On the other hand, NF1-associated high-grade gliomas represent an epigenetically heterogeneous group sharing typical high-grade histological aspects." (PMID 40277798, 2025). "We specifically chose comparisons to untreated, rather than vehicle-treated, mice to more accurately reflect clinical practice where many children with NF1-associated low-grade glioma are monitored and untreated." (PMID 41497446, 2025). "Taken together, our data suggest that RECQL4 plays a role in the biology of gliomas and MPNSTs, with higher expression in high-grade gliomas and lower expression in MPNSTs, particularly NF1-associated cases." (PMID 41317405, 2025). "This signaling cascade ultimately affects NF1-associated low-grade glioma cells in the optic pathway, promoting their survival and progression." (PMID 40092993, 2025). "Emerging strategies, including bevacizumab for symptom control and MEK inhibitors for NF–1-associated gliomas, show promise, while immunotherapy and CAR T-cell therapy hold potential to transform the therapeutic landscape." (PMID 40867225, 2025). "Taken together, these findings demonstrate that optic nerve crush is sufficient to induce glioma formation in mice with progenitor cell Nf1 loss." (PMID 38308315, 2024). "Although RAS genes are infrequently mutated in human GBM, they are highly expressed in glioma tissues or activated in NF1‐loss GBMs, leading to frequent activation of RAS pathways." (PMID 38828688, 2024).
glioma (continued). "Individuals with NF1 possess a genetic predisposition to central nervous system neoplasms, particularly gliomas affecting the visual pathway, known as optic pathway gliomas (OPGs)." (PMID 38804352, 2024). "Using two distinct brain injury paradigms and several different genetically engineered mouse strains, we establish that CNS injury is sufficient to induce glioma formation in mice harboring Nf1-deficient neuroglial progenitor cells." (PMID 38308315, 2024). "The natural history of ONG is usually indolent for NF-1-associated tumours and aggressive in spontaneous gliomas." (PMID 39816384, 2024). "Trametinib is a MEK1/2 inhibitor that has been found to be effective for treatment of BRAF V600E-mutated gliomas, and it is also being tested in the treatment of patients with NF1 mutations." (PMID 39684714, 2024). "Other cancer syndromes such as Li-Fraumeni or NF-1 have also been associated with increased risks of developing glioma." (PMID 38243010, 2024). "Individuals with NF1 have a significantly higher risk of developing low-grade gliomas compared to high-grade gliomas." (PMID 39273062, 2024). "As such, one risk modifier, asthma, reduces glioma incidence in children with NF1 and in Nf1-OPG mice." (PMID 38308315, 2024). "Within the gliomas associated with NS, the optic pathway tumors are rare, but are frequently manifested in about 15% of patients with NF-1 below the age of 6 years." (PMID 39336782, 2024). "Further insights into the putative role of T cells in NF1 tumor initiation can be gleaned from studies in NF1-associated low grade gliomas (LGGs)." (PMID 38473354, 2024). "For example, neurofibromatosis-1 (NF1) deficiency in gliomas is associated with increased infiltration of TAMs." (PMID 38254796, 2024). "As an important part of RAS signaling activation, NF1 can be deleted or mutated somatically or at the constitutional level in gliomas." (PMID 36831610, 2023). "Intriguingly, studies have shown that NF-1-mutated mice exposed to a dark environment during the period of glioma development exhibit tumors with a lower level of proliferation." (PMID 37830595, 2023). "NF1 is associated with an increased risk of glioma, and PAs represents about half of all NF1-associated gliomas." (PMID 36831464, 2023). "Targeting oncogenic drivers is already a cornerstone of treatment for a subset of glioma patients, most notably those with Neurofibromatosis 1 (NF1) mutations, BRAF fusions and BRAFV600E mutated LGG and HGG." (PMID 37781183, 2023). "Optic pathways gliomas (OPGs) fall into two categories: benign gliomas of childhood, a tumor often associated with neurofibromatosis type 1 (NF-1), and malignant glioma." (PMID 37830595, 2023). "One such model, Nf1OPG (Nf1flox/−; Gfap-Cre) mice, recapitulates the genetics of NF1 patients: the mice harbor a germline Nf1 mutation in all cells and a second-hit Nf1 loss in the glioma-initiating neural stem cells." (PMID 37891793, 2023). "In 42–60% of cases, it occurs in the cerebellum, while 9% to 30% cause gliomas of the optic nerve and hypothalamus, as well as those associated with NF1 mutations." (PMID 37959175, 2023). "Selumetinib is a MEK inhibitor recently studied in NF1-associated low-grade glioma by the Pediatric Brain Tumor Consortium (PBTC)." (PMID 37046770, 2023). "The defining role of the MAPK pathway in the pathogenesis of glioma was first suggested by the high prevalence (10% to 15%) of OPGs in patients with germline NF1 mutation." (PMID 37124503, 2023). "To assess the effect of ATRX depletion in high-grade glioma cell lines that are NF1 deficient and grow easily, and therefore are more feasible for functional experiments, we selected U251 and SF188." (PMID 35740680, 2022). "The other 11 gliomas demonstrated two or more somatic events contributing to inactivation of the remaining wild-type NF1 allele." (PMID 35945463, 2022).
glioma (continued). "Through next-generation sequencing, copy number analysis, and DNA methylation profiling of gliomas from 47 NF1 patients, we identified 2 molecular subgroups of NF1-associated gliomas." (PMID 35945463, 2022). "Our re-analysis of DNA methylation profiles from this prior NF1-associated low-grade glioma cohort found that the majority aligned with our novel methylation subclass of NF1-associated pilocytic astrocytomas." (PMID 35945463, 2022). "Another integrated molecular analysis of 70 low-grade glioma cases with NF1 tumors revealed 3 FGFR1 hotspot mutation." (PMID 35018490, 2022). "As such, we believe NF1-associated low-grade gliomas should be regarded as a distinct biologic entity and henceforth classified as “pilocytic astrocytoma, arising in the setting of NF1”." (PMID 35945463, 2022). "The efficacy of MEK inhibitors has previously been shown in NF1-deficient glioblastoma cell lines, in addition to clinical benefit in refractory neurofibromatosis-associated glioma harboring the NF1 mutation." (PMID 34737188, 2022). "Genome-wide DNA methylation profiling was performed on 32 NF1-associated gliomas from this patient cohort." (PMID 35945463, 2022). "Given the wide histologic spectrum of NF1-associated gliomas, improved stratification schemes incorporating histologic, genetic, and epigenetic features will better guide management for this patient population." (PMID 35945463, 2022). "ADCY8 polymorphisms are accompanied by the risk of glioma (brain tumor) in patients with neurofibromatosis type 1 (NF1), which is sex-specific." (PMID 35832555, 2022). "Prospectively, DNA methylation testing revealing that a patient’s glioma epigenetically aligns with this group should prompt consideration of underlying NF1." (PMID 35945463, 2022). "Through multiplatform molecular profiling, we identified two molecular groups of NF1-associated gliomas with divergent clinical outcomes." (PMID 35945463, 2022). "The TCGA data analysis indicated that glioma patients carrying NF1 somatic mutations have worse overall survival (median survival time: smoking 19.9 months vs. non-smoking 36.8 month; P = 0.0018)." (PMID 36352461, 2022). "There was also monosomy or copy-neutral loss of heterozygosity of chromosome 17q in the majority of gliomas across both molecular groups that functioned as the mechanism for eliminating the remaining wild-type NF1 allele located at 17q11.2." (PMID 35945463, 2022). "An ongoing phase III study (NCT03871257) is evaluating selumetinib in comparison with chemotherapy in low-grade NF-1-associated gliomas." (PMID 35875139, 2022). "Relatedly, clonal evolution of NF1-associated gliomas and the mechanisms of tumor progression and treatment resistance remains poorly understood." (PMID 35945463, 2022). "Targeting the PI3-kinase-Akt-mTOR signaling pathway with the mTOR small molecule inhibitor everolimus has also shown promising efficacy in a phase II clinical trial for children with recurrent/progressive NF1-associated low-grade gliomas." (PMID 35945463, 2022). "Different NF1 germline mutations in pediatric glioma patients that affected the splicing process have been described: c.205_205insTC, c.1185+1G>A, c.889-2A>G, c.2325+1G>A, and c.1260+1G>T in pilocytic astrocytomas and OPG." (PMID 36497448, 2022). "In 36 of the 47 gliomas, the second NF1 allele was somatically inactivated by a single event, most often via LOH (n = 22) or less frequently via truncating or missense mutation (n = 12) or structural rearrangement (n = 2)." (PMID 35945463, 2022). "Alterations in NF1 predispose to increased risk of central nervous system tumors, of which gliomas are the most common subtype in this patient population." (PMID 35821680, 2022).